TNF (tumor necrosis factor)
Diseases named in the same sentence as TNF in open-access papers (continued):
Sharing a sentence is not in itself a finding about the gene and the disease.
Anxiety (continued). "Interestingly, adolescents who were characterised by increased Amg activity after exposition to human faces expressing fear and anxiety also showed increased levels of TNF-α." (PMID 40362590, 2025). "In the MIA mouse model of ASD, P. goldsteinii MTS01 ameliorated antisocial and anxiety-like behaviors by reducing colonic TNF-α, IL-6, and IL-1β in the intestines while increasing the activity of antioxidant pathways and decreasing glutamate receptor signaling in the hippocampus." (PMID 40804450, 2025). "In addition, the pro-inflammatory cytokines TNF-α and IL-1β have been reported to induce anxiety-like behaviors." (PMID 40906736, 2025). "In addition, SCFAs can modulate microglia activation, influencing the release of pro-inflammatory factors, such as IL-1β, IL-6, and TNF-α, which can further impact neuroinflammation and anxiety-like behaviors." (PMID 41459223, 2025). "Furthermore, it has been shown that exercise reduces inflammatory markers, such as C-reactive protein (CRP), interleukin-6 (IL-6), and TNF-α, thus reducing chronic inflammation-triggered anxiety symptoms." (PMID 41144483, 2025). "In our previous study on an epilepsy model, we showed that fenoprofen exerts neuroprotective effects by reducing inflammatory mediators such as TNF‐α and NF‐κB in the hippocampus and improves cognitive behaviors including anxiety‐like behaviors, memory, and learning." (PMID 39907374, 2025). "Additionally, serum TNF concentrations were elevated in Sprague-Dawley rats exposed to restraint and forced swim stress, whereas treatment with anti-TNF antibodies ameliorated anxiety-like behavior." (PMID 40724875, 2025). "Moreover, nuclear factor kappa-B (NF-κB), tumor necrosis factor-α (TNF-α) and IL-1β produced by activated microglia in the BLA are associated with anxiety- and depressive-like behaviors in mice." (PMID 41276822, 2025). "In addition, commonly used psychiatric drugs (including anti-depressants, anticonvulsants, and anti-anxiety drugs that were taken by several of the patients in the OA cohort) have been shown to reduce key inflammatory cytokines such as IL-6 and TNF-α." (PMID 40565171, 2025). "Given the anatomical and functional connectivity of the retina to emotion-regulating brain regions, it is plausible that TNF-α released from apoptotic RGCs may propagate signals through similar retinal-hypothalamic-limbic pathways to modulate anxiety." (PMID 41234418, 2025). "Furthermore, it was demonstrated that mononuclear cells in the plasma of these patients, in comparison to healthy individuals, produce higher levels of tumor necrosis factor-alpha (TNF-alpha), which has been linked to the degree of anxiety." (PMID 39274340, 2024). "The elevation of these cytokines (especially IL-1β, IL-6, IL-10, IFN-γ, and TNF-α) may have a role in stress and anxiety in infected patients." (PMID 39935742, 2024). "In addition, anxiety has been found to be significantly positively correlated with TNF-α levels in related studies focusing on PD patients." (PMID 39295596, 2024). "We evaluated whether curcumin supplementation for 15 consecutive days (1800 mg/day) would decrease systemic MCP-1, sCD14, and TNF alpha levels in patients with moderate anxiety (n = 81)." (PMID 39334711, 2024). "Moreover, pro-inflammatory cytokines (TNF-α and IL-1β), which are linked to microglia and can activate microglia, and the ACC are associated with anxiety." (PMID 39337650, 2024). "Furthermore, anxiety became increasingly prominent as the levels of·OH and TNF-α in serum were elevated." (PMID 38755545, 2024). "DHA and EPA may suppress the release of inflammatory cytokines, including TNF-α, Interleukin 1 (IL-1), IL-2, and IL-6, which may have an anti-anxiety or anti-depressive effect." (PMID 38979505, 2024). "Furthermore, administering TNF-α neutralizing antibodies to rodents has been found to reduce their anxiety-like behavior." (PMID 39720795, 2024).
Anxiety (continued). "Combining isolated CD8+ T cell RNA sequencing and flow cytometry, we provide compelling evidence that the HBV-induced decline in hippocampal neurogenesis and the manifestation of anxiety-like behaviour are mediated by infiltrating CD8+ T cells through TNF-α-dependent mechanisms." (PMID 39386089, 2024). "Abolishing TNF-α production in these animals mitigated the stress-induced anxiety changes." (PMID 38381770, 2024). "Tumor necrosis factor α (TNF-α) serves as an essential mediator in the stress response of mice, with it being crucial for stress-induced synaptic potentiation in the ventral hippocampus and for the elevation of anxiety-like behavior." (PMID 38785554, 2024). "TNF-α and IL-6 may contribute to the onset of anxiety symptoms in MSA patients through these mechanisms." (PMID 39295596, 2024). "This study aimed to evaluate whether curcumin supplementation for 15 consecutive days (1800 mg/day) could reduce systemic MCP-1, sCD14, and TNF alpha levels in patients with moderate anxiety." (PMID 39334711, 2024). "The stress-induced increase in hippocampal TNF-α levels could influence how stress affects anxiety-like behaviors." (PMID 38381770, 2024). "Considering that TNF-α regulates the transcription of the NLRP3 inflammasome, the increased expression of NLRP3 observed in the AMG might also be involved in the anxiety and depressive-like behaviors associated with CCI-induced neuropathic pain." (PMID 37891937, 2023). "Central administration of CpdA to adult mice blunted LPS-induced hypolocomotion and anxiety-like behavior and reduced TNF-α, IL-1β and IBA-1 (microglia marker) mRNA in the NAc, a brain region modulating anxiety and motivation and implicated in neuroinflammation-induced mood deficits." (PMID 38111048, 2023). "On the other hand, TNF-α accumulates in the PrL and further promotes the activity of BLA neurons by targeting PrLBLA neurons, which causes anxiety phenotypes and may further disturb pain perception." (PMID 36917193, 2023). "Similarly, an animal study on obese rats reported decreased anxiety-like behaviour after DHA/EPA supplementation associated with a reduced plasma concentration of IL-6 and TNF-α, as well as suppressed TNF-α synthesis in the prefrontal cortex." (PMID 37240914, 2023). "To test whether TNFR1 mediated the effects of TNF-α on chronic pain-induced anxiety, we knocked down Tnfr1 specifically in PrLBLA neurons with an injection of retrograde AAV-Cre virus into the BLA and AAV-DIO-Tnfr1-shRNA-eGFP into the PrL." (PMID 36917193, 2023). "Moreover, mechanistic studies indicated that elevated TNF-α/TNFR1 signaling in the PrL caused increased insertion of GluA1 receptors into PrLBLA neurons and contributed to anxiety-like behaviors in mice with chronic pain." (PMID 36917193, 2023). "Notably, there exists a connection between anxiety and increased levels of TNF-α following acute stress." (PMID 37687297, 2023). "Thus, chronic high-fat diet consumption promoted anxiety behavior together with an increased level of the inflammatory cytokines IL-1β, IL-6, and TNF-α in the hippocampus." (PMID 37373230, 2023). "A systematic review showed risk factors for nonadherence to anti-TNF therapy include female sex, smoking, anxiety, and moodiness." (PMID 39132037, 2023). "Next, we examined whether injections of IL-1β and TNF-α in the gums can modulate anxiety-like behavior and cognitive functions of mice." (PMID 36915108, 2023). "This could attenuate Th1 cell‐mediated immune responses and inhibit the synthesis of cytokines including TNFα, thereby, dampening neuroinflammation and reducing anxiety and depressive symptoms and improving sleep quality for up to 8 weeks post‐treatment." (PMID 36178333, 2023). "To examine whether TNF-α in the PrL plays a role in pain perception or anxiety-like behaviors, we injected recombinant TNF-α protein directly into the PrL region of WT mice." (PMID 36917193, 2023).
Anxiety (continued). "However reduced SD-induced anxiety-like behavior and decreased levels of pro-inflammatory cytokines including TNF-α and IL-1β were observed in the hippocampus of rats after 7 days of FG intervention." (PMID 37377643, 2023). "Additionally, the intervention of CLM + SSRI significantly improved the symptoms of anxiety and insomnia, and reduced serum IL-6 and TNF-α levels." (PMID 37808199, 2023). "Alteration of the periphery immune system could affect CNS immune system and induce anxiety‐like behavior, therefore we further measured the levels of IL‐1β, TNF‐α, and IL‐10 in the hippocampus." (PMID 37157948, 2023). "However, like the standard drug EZ group, FGL and FGH demonstrated improved anxiety-like behavior and reduced levels of TNF-α and IL-1β in the hippocampus of SD rats 7 days after the intervention." (PMID 37377643, 2023). "Interestingly, TNF-α on D1 and D3, IL-6 on D3, IL-8 on D3 and D7, and IL-17A on D1, D3, and D7 correlated with higher anxiety rate (all P<0.05)." (PMID 37878890, 2023). "Anxiety PCQ behavioral scores from parents were significantly worse with antenatal expression of 11 gene variants involved with estrogen (p = 0.000005), leptin (p = 0.0002) and TNF alpha signaling (p = 0.0003)) within social communication regions." (PMID 35883654, 2022). "In contrast, treatment with TNF-α and IL-1β inhibitors could suppress the development of anxiety in mouse models." (PMID 35209199, 2022). "We also demonstrated in mice that METH induced anxiety-like symptoms during acute withdrawal and significantly increased the level of the serum proinflammatory cytokine TNF-α, while exercise was able to resist the METH-induced increase in serum TNF-α levels and improve anxiety symptoms." (PMID 36106141, 2022). "Furthermore, in a rat model of LPS-induced anxiety, honey had protective effects against anxiety by decreasing the expression levels of TNF-α and IL-6." (PMID 36358502, 2022). "This suggests that it is possible that stress-induced anxiety is mediated by TNF." (PMID 36104437, 2022). "In our study, TNF-α was negatively correlated with anxiety at TNM stages II to IV." (PMID 36405903, 2022). "We also used lipopolysaccharide (LPS), an agonist of TLR4, in an in vitro model of macrophage IL-1β and TNF release and in an in vivo paradigm of “sickness behavior,” measuring inflammation-induced signs of anxiety, hypolocomotion, and suppressed exploration in mice." (PMID 36091684, 2022). "This may have therapeutic potential for cases in which the effects of stress are particularly detrimental as in post-traumatic stress disorder, where TNF-based therapeutics may hold potential to treat the chronic anxiety of such conditions." (PMID 36104437, 2022). "Notably, the correlations of TNF‐α and IL‐1β with anxiety seemed to be stronger than IL‐6 and IL‐17." (PMID 34697903, 2022). "Moreover, elevating central TNF levels by direct intracerebroventricular injection increases anxiety-like behaviors in mice." (PMID 36104437, 2022). "This could suggest that multiple cytokines are involved with the induction of the stress response but perhaps TNF has a unique role in maintaining the anxiety." (PMID 36104437, 2022). "Mice challenged intraperitoneally with S. aureus showed increase of anxiety‐like behaviors, which may be mediated by the overexpression of IL‐6 and TNF‐α in prefrontal cortex and hippocampus." (PMID 35977050, 2022). "In addition, a red pomegranate fruit extract-based formula ameliorated anxiety-like behaviors through reducing the levels of serum inflammatory cytokines NF-κB, TNF-α, IL-6, IL-1β and IFN-γ." (PMID 36358502, 2022). "Mice with a specific deletion of TNF from astrocytes (using GFAP-Cre combined with floxed TNF alleles) have an equivalent increase in anxiety-like behaviour following stress as their Cre negative littermates." (PMID 36104437, 2022).
Anxiety (continued). "Here we reveal that Tumor Necrosis Factor α (TNF) is a required downstream mediator of the stress response in mice, necessary for stress-induced synaptic potentiation in the ventral hippocampus and for an increase in anxiety-like behaviour." (PMID 36104437, 2022). "A blockade of TNF‐α has also been shown to reduce anxiety‐like behavior and inflammation in mice." (PMID 34878231, 2022). "In fact, alteration in redox balance, increased reactive oxygen species (ROS) production and high circulating inflammatory cytokines such as interleukin (IL)-1, IL-6, and tumor necrosis factor (TNF) have been detected both in anxiety patients and stressed animal models of anxiety." (PMID 36077225, 2022). "Comparisons to psychosocial measures of anxiety reflected a significant negative association between TNF-α/IL-10 ratio and Preparation for Labor (p = 0.03) and for Relationship with Spouse/Partner (p = 0.01) in pregnancy for the control group." (PMID 34360332, 2021). "Considering the crucial role of this cytokine in anxiety, we can speculate that the high hippocampal TNF-α levels can contribute to sustain an anxiety behavior in BTZ mice." (PMID 34638592, 2021). "Interestingly, two studies measured plasma pro-inflammatory cytokines such as IFN-γ and TNF-α after probiotic treatment, obtaining reduced levels as anxiety decreased." (PMID 33652962, 2021). "As risk factors (age, sex, anxiety, anti-TNF treatments) do not similarly affect migraine and neuropathic pain, this suggests that these two pain syndromes do not rely on the same mechanisms." (PMID 32560321, 2020). "In addition, they reported increases in anxiety-like behavior and hippocampal TNF-a and IL-1β, as well as decreases in depression-related symptoms, in EAE-induced mice." (PMID 33066156, 2020). "Exposure to 6 weeks of repeated injection resulted in an anxiety-like phenotype, decreased systemic inflammation (i.e., reduced plasma levels of TNFα and IL4), increased corticosterone reactivity, increased microglial activation and decreased neuronal differentiation in the dentate gyrus (DG)." (PMID 32958745, 2020). "Finally, immunomodulating drugs, such as anti-TNF-α drugs, anti-IL-6 monoclonal antibodies, and other biologics, appear to ameliorate anxiety and depressive symptoms in patients with RA." (PMID 33365319, 2020). "However, CVE attenuated the expression of pro-inflammatory cytokines TNF-α and IL-6 and was generally effective at enhancing motor function and reducing anxiety-like behavior in Tg-SwDI mice, though alterations in learning and memory tasks were varied." (PMID 31296239, 2019). "TNFα regulates a wide range of physiological functions controlled by the hypothalamus and hippocampus including sleep, food intake, learning, memory and anxiety-like behaviors." (PMID 31026287, 2019). "Other recent studies report that diets high in sugars, processed foods (i.e., meat products), and/or fats are related with higher anxiety levels through alterations of glucose, protein and energy homeostasis, and increases in inflammatory cytokines (i.e., IL-6, IL-1β, TNFα) and corticosterone." (PMID 31159322, 2019). "Moreover, humans experimentally treated with LPS display increased anxiety as well as increases in IL-6 and TNF-α, 2 to 3 hrs thereafter, being the changes in IL-6 more pronounced involved in their anxiety status." (PMID 30133465, 2018). "Our findings revealed that mice subjected to CMS exhibited anxiety- and depressive-like behaviors in the sucrose preference test, elevated plus maze, and forced swim test, along with increased interferon-γ, tumor necrosis factor-α, and indoleamine 2,3-dioxygenase-1 levels in the hippocampus." (PMID 30459574, 2018). "Similarly, others report that mice with complete Freund’s adjuvant-induced inflammatory pain showed anxiety-like behavior and increased TNF-α in the BA." (PMID 30208926, 2018).
Anxiety (continued). "We examined the effects of Xiaoyaosan on behaviours exhibited in the elevated plus maze test, open field test and novelty-suppressed feeding test as well as hippocampal neuron damage and changes in the TNF-α/JAK2-STAT3 pathway in a rat model of chronic immobilization stress (CIS)-induced anxiety." (PMID 28336920, 2017). "In our study, NNAV showed a potential to reduce the anxiety-like behavior, and these may be due to the inhibitory effect on the secretion of IL-6 and TNF-α." (PMID 25093033, 2014). "The chemokines or inflammatory cytokines such as IL-6 and TNF-α production in MRL/lpr mice may be involved in anxiety behaviors." (PMID 25093033, 2014). "We measured the effect of low, medium, and high Ω-3:Ω-6 dietary ratio, given from the age of 3–7 months, on anxiety and cognition-like behavior, hippocampal tissue expression of TNF-α, markers of neuronal progenitor proliferation and gliogenesis and serum cytokine concentration." (PMID 25484856, 2014). "Performing screening MRI on all such patients considering anti-TNF-α therapy is not feasible from a resource perspective, and the use of MRI in this way confers a risk of significant anxiety in patients as a result of incidental diagnoses with varying degrees of clinical significance being revealed." (PMID 41317369, 2026). "Furthermore, we suggest that pro-inflammatory cytokines such as TNF-α and IL-6-key indicators of stress-induced inflammation-may serve as predictors of anxiety-related vulnerability." (PMID 41853172, 2026). "However, direct evidence-such as in vivo observations of anxiety-like behaviors induced by retinal TNF-α overexpression or neutralization in animal models of glaucoma—remains lacking, highlighting a critical direction for future research to confirm this bidirectional pathological link." (PMID 41234418, 2025). "Elevated levels of TNF-α and IL-6 may inhibit the synthesis and release of neurotransmitters such as serotonin and dopamine, thereby leading to mood dysregulation disorders like anxiety." (PMID 39295596, 2024). "Oxidative stress, high levels of cytokines (TNF-α, IL-1β, IL-6, IL-10), and dysregulation of the proliferation and differentiation of oligodendrocytes and astrocytes were observed in the prefrontal cortex and hippocampus of T1D mice exhibiting concomitantly anxiety-like behavior." (PMID 38279738, 2024). "Therefore, it is conceivable that infiltrating CD8+ T cells may impede hippocampal neuron proliferation and modulate anxiety through the remote action of cytokine TNF-α." (PMID 39386089, 2024). "Studies in mice, dogs, and horses have shown that CBD reduces the production of inflammatory cytokines such as tumor necrosis factor alpha (TNFα), which may help to reduce inflammation in various tissues and promote a calming effect and reduced anxiety in horses." (PMID 38379920, 2024). "Several studies conducted in mice and horses, have shown that CBD reduces the production of inflammatory cytokines such as tumor necrosis factor-α (TNFα) which may reduce inflammation in various body tissues and may have a calming and analgesic effect and lessen anxiety in horses." (PMID 39720409, 2024). "Therefore, suitable clinical intervention on the anxiety may have potential benefits in MSA by monitoring the serum TNF-α and IL-6 levels." (PMID 39295596, 2024). "Studies conducted in mice and horses have shown that CBD reduces the production of inflammatory cytokines such as tumor necrosis factor-α (TNFα), which may help reduce inflammation in various body tissues or may have a calming effect and lessen anxiety in horses." (PMID 36670785, 2023). "Moreover, bergamot essential oil could relieve anxiety-like behaviors of aluminum trichloride-exposed rats via downregulating the levels of IL-1β, IL-6 and TNF-α in the hippocampus and the frontal cortex." (PMID 36358502, 2022).